WT1 (WT1 transcription factor)
Diseases named in the same sentence as WT1 in open-access papers (continued):
Sharing a sentence is not in itself a finding about the gene and the disease.
sarcoma (continued). "Our differentials were ruled out due to the negative immunohistochemistry of NKX2.2, WT1, S-100, HMB-45, Desmin, and PanCK that ruled out Ewing sarcoma, CIC-DUX4 sarcoma, clear cell sarcoma of soft tissue, rhabdomyosarcoma, and synovial sarcoma, respectively." (PMID 40932977, 2025). "The morphology was not typical for gastroblastoma and was negative for CD99, ERG, and WT1, which were against CIC/DUX sarcoma." (PMID 36928336, 2023). "External consultation indicated that the tumor cells were focally positive for WT1 and ETV4, consistent with CIC-rearranged sarcoma; however, CIC FISH did not identify the CIC gene rearrangement." (PMID 36033527, 2022). "These include sarcomas with BCOR alterations, CIC-rearranged sarcoma (see ‘WT1 and ETV4’), and round cell sarcoma with EWSR1-non-ETS fusions." (PMID 33921435, 2021). "On the contrary, ES, BCOR rearranged sarcoma, and poorly differentiated synovial sarcomas, are negative for both nuclear ETV4 and WT1 staining." (PMID 32155762, 2020). "While WT1 and CD99 staining are sensitive, they are not specific for CIC-rearranged sarcomas." (PMID 40599504, 2025). "While CIC-rearranged sarcomas tend to be positive for CD99, WT1, ETV4, and DUX4, these stains are fairly nonspecific and are not sensitive enough to be used alone, thus, there remains a need for specialized genetic testing such as RNA sequencing or RT-PCR for confirmatory diagnosis." (PMID 40599504, 2025). "The tumor had no expression of ETV4 and WT1, markers typically positive in CIC-rearranged sarcoma and which may be useful in this differential diagnosis." (PMID 34898574, 2021). "Histologically, we never observed sarcomas or lymphomas arising in electroporated animals and, accordingly, all tumors analyzed expressed molecular hallmarks of human HGSOC, including Cytokeratin-7 (CK7), Wilms Tumor 1 (WT1), Cancer Antigen 125 (CA-125), Paired box 8 (Pax-8), and high Ki67." (PMID 35082152, 2022).
WAGR syndrome (46 papers, 2008 to 2025). WAGR syndrome (Wilms tumor - aniridia - genitourinary anomalies - intellectual disability mental retardation) is a rare genetic disorder characterized by an unusual complex of congenital developmental abnormalities with intellectual disability, and an increased risk of developing Wilms tumor. "The absence of aniridia, cardiac, and pulmonary malformations, as well as the presence of normal intellectual development, allowed for the exclusion of WAGR syndrome and Meacham syndrome—two WT1-associated disorders typically linked to reduced life expectancy." (PMID 40426774, 2025). "The mutation, combined with a WT1 mutation, is a hallmark in WAGR syndrome, known to cause aniridia and WTs." (PMID 40439002, 2025). "The typical deletion in WAGR syndrome includes the WT1 and PAX6 genes, but larger deletions can be associated with obesity and neurobehavioral abnormalities." (PMID 26605098, 2015). "The rate of deterioration of kidney function varies according to the syndrome, with a much earlier onset of kidney failure described in children with DDS (due to intragenic WT1 pathogenic variants) than in those with a complete deletion of one allele of WT1, as in WAGR syndrome." (PMID 34608521, 2022). "WAGR syndrome is associated with 11p13 deletion encompassing the WT1 gene." (PMID 28716159, 2017). "Heterozygous pathogenic variants in PAX6 are typically associated with autosomal dominant aniridia, or are part of the Wilms tumor-aniridia-genital anomalies-range of developmental delay (WAGR) syndrome if the whole gene is deleted along with WT1." (PMID 41011222, 2025). "The size of deletion of 11p13 varies between 1 megabase to 26.5 megabase; however, even a 700 kilobase deletion deleting both WT1 and PAX6 genes can cause WAGR syndrome." (PMID 39600756, 2024). "Aniridia also occurs in the WAGR syndrome that is associated with hemizygosity for the PAX6 gene and deletions of 11p13 including WT1." (PMID 37578539, 2024). "The deletion of chromosome 11p13 involving the WT1 and the PAX6 genes has been shown to cause WAGR syndrome." (PMID 36011342, 2022). "We identified different heterozygous deletions affecting the PAX6 and WT1 genes on chromosome 11p13 in all six probands with WAGR syndrome." (PMID 36011342, 2022). "In familial aniridia cases, the chance of a WT1 deletion is very low, with only two WAGR syndrome familial cases reported." (PMID 30242502, 2019). "For cases in which the contiguous gene Wilms tumor 1 (WT1; OMIM 194070; 11p13) is also disrupted, affected children are typically syndromic and at risk for juvenile Wilms tumor of the kidney (WAGR syndrome, OMIM 194072)." (PMID 21423868, 2011). "Eight probes were screened in the 11p13 region associated with WAGR syndrome, in BDNF (2 probes), PAX6 (3 probes), WT1 (2 probes) and HIPK3 (1 probe)." (PMID 18925931, 2008). "Aniridia may also be caused by large genomic deletions encompassing PAX6 and Wilms tumor 1 (WT1), contiguous genes separated from each other by 700 kb, resulting in WAGR syndrome." (PMID 37542296, 2023). "We identified 26 patients with WT and constitutional WT1 pathogenic variant and one patient with a complete phenotype of WAGR syndrome who had no documented analysis of WT1 pathogenic variant but is assumed to have a constitutional deletion." (PMID 34608521, 2022). "Subsequent to germline WT1 loss, the second somatic event leading to WT formation in patients with WAGR syndrome is commonly intragenic WT1 mutation, rather than a second 11p genomic loss, as the latter is likely to be cell lethal." (PMID 28716159, 2017). "Deleted genes in the region including WT1 and PAX6 are thought to cause the phenotypic features and clinical issues in patients; however, much is still unknown about the specific molecular role of these genes in patients with WAGR syndrome." (PMID 34970513, 2021).
WAGR syndrome (continued). "However, since his aniridia is a consequence of an internal mutation within the PAX6 gene rather than a contiguous gene deletion including WT1, neither he nor his offspring will be at increased risk for the WAGR syndrome." (PMID 23799907, 2013). "The deletion located in the region 11p14.1p13 included, among others, the WT1 (MIM #607102) and PAX6 (MIM #607108) genes, which correlated with the clinical phenotype of WAGR syndrome in the patient." (PMID 38069245, 2023). "A small proportion of the sporadic cases have WAGR syndrome (OMIM194072), a 11p13 contiguous gene deletion syndrome involving PAX6 and WT1 genes." (PMID 35614435, 2022). "For those with sporadic aniridia, 33% of patients are diagnosed with WAGR syndrome, a contiguous gene deletion syndrome involving PAX6 and WT1." (PMID 34573386, 2021). "Approximately one third of patients with sporadic aniridia ultimately develop WAGR syndrome due to a contiguous gene deletion syndrome involving both PAX6 and WT1." (PMID 34573386, 2021). "The best known syndromic form is WAGR syndrome (OMIM 194072) — a contiguous genes deletion syndrome of the 11p13 region (encompassing the PAX6 and WT1 genes)." (PMID 29460221, 2018). "Genetic testing confirmed a heterozygous alteration in PAX6 (c.495delG, p.Thr166Leufs*41) and no abnormalities of WT1, excluding WAGR syndrome." (PMID 32056389, 2020). "The infant's genetic testing confirmed a heterozygous alteration in Exon 7 of PAX6 (c.495delG, p.Thr166Leufs*41) and a negative WT1 which excluded WAGR syndrome." (PMID 32056389, 2020).
pancreatic cancer (44 papers, 2008 to 2025). "In the case of WT1 peptide vaccines, several approaches have confirmed their low risk of side effects and feasibility for the treatment of solid tumors like pancreatic cancer as well as AML and myelodysplastic syndrome (MDS)." (PMID 30678050, 2019). "A WT1 peptide-pulsed DC vaccine was tested in a pilot phase I trial in eight patients with resected pancreatic cancer." (PMID 40723238, 2025). "No significant adverse effects were reported, and seven out of eight patients with surgically resected pancreatic cancer exhibited durable WT1-specific CTL immune responses." (PMID 38430289, 2024). "Despite these limitations, the risk-benefit profile of cancer vaccines is encouraging, especially for the WT1 vaccine in the treatment of advanced pancreatic cancer." (PMID 38665761, 2024). "Another Phase 1 trial investigated the administration of WT1-pulsed DCs alongside gemcitabine and oral 5-FU (S-1) in eight patients with resectable pancreatic cancer." (PMID 39329989, 2024). "The transcription factor Wilm’s tumor gene 1 (WT1) is crucial in cancer, including pancreatic cancer." (PMID 38255288, 2024). "The patient was administered a three-drug combination of antigen-pulsed DCs loaded with WT1 peptides (highly expressed in pancreatic cancer), S-1, and OK-432 (an adjuvant for the WT1-DC vaccine)." (PMID 38430289, 2024). "This review aims to systematically summarize the clinical trials investigating the efficacy and safety of WT1 vaccines in patients with advanced pancreatic cancer." (PMID 38665761, 2024). "On the other hand, there are reports of prolonged OS in pancreatic cancer patients when WT1-DC is combined with multi-agent chemotherapy." (PMID 38143707, 2023). "It has also been shown that WT1-CTLs are induced by WT-DC administration in pancreatic cancer patients undergoing chemotherapy, and a higher number of CTLs is associated with a longer OS." (PMID 38143707, 2023). "We previously reported that DTH against the WT1 peptide correlated with favorable prognosis in WT1 peptide vaccines for patients with pancreatic cancer and glioblastoma multiforme." (PMID 36672344, 2023). "We, therefore, compared DTH and IPS by WT1-DC in a group of stage IV lung and pancreatic cancer patients in similar physical conditions." (PMID 38143707, 2023). "A Phase I clinical trial of a DC vaccine pulsed with Wilms’ tumor 1 (WT1)-specific MHC class I/II-restricted epitope for pancreatic cancer in combination with chemotherapy was reported." (PMID 37509288, 2023). "A phase I trial to investigated the safety and efficacy following treatment with DCs pulsed with a mixture of three types of WT1 peptides in combination with chemotherapy in pancreatic cancer and intrahepatic cholangiocarcinoma." (PMID 37064113, 2023). "Based on these characteristics, we compared DTH and IPS of WT1-DC treatment in patients with end-stage lung and pancreatic cancer with similar physical conditions." (PMID 38143707, 2023). "Here, we analyzed MPE samples taken from a patient with pancreatic cancer who received a dendritic cell vaccine targeting Wilms’ Tumor 1 (WT1) antigen over the disease course (two points at MPE1st and 2nd, two months after MPE1st)." (PMID 36293034, 2022). "Gemcitabine was shown to enhance the expression of the Wilms tumor gene 1 (WT1) and induced the sensitivity of pancreatic cancer cells to WT1-specific T cell-mediated antitumor immune response." (PMID 35342400, 2022). "In conclusion, CD8+ T cells responding to WT1 or SMAD4P130L neoantigen expressed in EpCAM+ pancreatic cancer cells were detected in MPE." (PMID 36293034, 2022). "CD8+ T cells responding to WT1 or SMAD4P130L neoantigen expressed in very few EpCAM+ pancreatic cancer cells were detected in MPE." (PMID 36293034, 2022). "Currently, a phase III study of a dendritic cell vaccine loaded with WT1 peptides (TLP0-001) is being conducted in Japan in patients with advanced pancreatic cancer refractory to standard chemotherapy." (PMID 31997007, 2020).
pancreatic cancer (continued). "Recent studies showed that WT1 is activated in pancreatic cancer and that patients with elevated BASP1 levels have a significantly better prognosis than individuals whose cancer cells contain no BASP1 but high WT1 levels." (PMID 31944520, 2020). "Although curcumin inhibits pancreatic cancer cell proliferation via degrading WT1 protein, degrasyn decreases WT1 protein at lower concentration and presents more strong anti‐cancer activity than curcumin." (PMID 31845546, 2020). "The protein expression of WT1 was measured in pancreatic cancer cells, which were transduced with specific shRNAs for USP5, USP9x or USP14, respectively." (PMID 31845546, 2020). "GEM was also shown to support DC vaccination in murine pancreatic cancer models and in a phase I clinical study using WT1 peptide as vaccination antigen." (PMID 30630527, 2019). "Treatment with DCs pulsed with WT1 peptides and chemotherapy in advanced pancreatic cancer has been evaluated in several small series from Japan." (PMID 29946224, 2018). "Most experience with DC-based vaccination has been gathered for MUC1 and WT1 antigens, where clinical studies in advanced pancreatic cancer have provided encouraging results." (PMID 29946224, 2018). "Phase I clinical trials of DC vaccinations containing the WT1 class II peptide compatible with HLA-DRB1*04:05 (332–347: KRYFKLSHLQMHSRKH) have also been conducted in patients with pancreatic cancer." (PMID 26690485, 2015). "Chemoradiotherapy has also been shown to enhance the induction of WT1-CTLs in patients receiving WT1-targeted DC vaccinations for pancreatic cancer." (PMID 26690485, 2015). "We identified Igfbp1, Serpina1 and Wt1 genes that are likely to be clinically useful biomarkers for prognostic or therapeutic purposes in metastatic pancreatic cancer, particularly in pancreatic cancer where c-Myc is overexpressed." (PMID 18218118, 2008). "An extensive literature search was conducted on databases Medline, Web of Science, ScienceDirect, and Google Scholar using the keywords "Advanced pancreatic cancer," "Cancer vaccines," "WT1 vaccines," and "Pulsed DC vaccines," and the results were exclusively studied to construct this review." (PMID 38665761, 2024). "Lung and pancreatic cancers express WT1 more than 90% of the time, making WT1 a good immune target." (PMID 38143707, 2023). "Therefore, the correlation between DTH and IPS can be determined by examining the immune response of WT1-DCs in lung and pancreatic cancers." (PMID 38143707, 2023). "This study aimed to reveal the CD8+ T cell response to WT1 and individual neoantigens from memory T cell subsets in the immune suppressive environment using an MPE model sampled from a patient with pancreatic cancer who received the dendritic cell vaccination targeting the WT1 antigen." (PMID 36293034, 2022). "We then determined whether USP5 mediates degrasyn‐induced degradation of WT1 protein in pancreatic cancer cells." (PMID 31845546, 2020). "Finally, colony number was counted in degrasyn‐treated pancreatic cancer cells transduced with WT1 or NC." (PMID 31845546, 2020). "The WT1 gene is highly expressed specifically in pancreatic cancer." (PMID 31029154, 2019). "The WT1 protein is highly expressed (75%) in pancreatic cancers." (PMID 29946224, 2018). "Moreover, combined treatment with curcumin and siRNA targeting WT1 resulted in a significant inhibition of cell proliferation compared to curcumin-treated cells alone in pancreatic cancer cells." (PMID 22449094, 2012). "Indeed, gemcitabine enhanced WT1 expression in human pancreatic cancer cells and sensitized the pancreatic cancer cells with WT1-specific T cell-mediated antitumor responses." (PMID 21922022, 2011). "Therefore, degrasyn might be a promising agent for treatment with pancreatic cancer patients through degrading oncoprotein WT1." (PMID 31845546, 2020). "The Wilms’ tumor 1 (WT1) antigen has been recognized as a highly effective target in various cancer types, including pancreatic cancer." (PMID 41190066, 2025).
pancreatic cancer (continued). "Initially identified as a tumor suppressor, the Wilms’ tumor 1 (WT1) gene has been shown to display significant increases in expression across a range of human cancers, including lung and pancreatic cancer." (PMID 38499392, 2024). "The most prevalent peptides to pulse DC-based vaccines for pancreatic cancer include mucin 1 (MUC1) and Wilms tumor 1 (WT1)." (PMID 39329989, 2024). "WT1-specific central and effector memory CD8+ T cells were observed in cancerous pleural effusion in a patient with long-survival pancreatic cancer after WT1-pulsed DC vaccination." (PMID 37509288, 2023). "In a study of mostly pretreated patients with unresectable advanced pancreatic cancer, participants received a WT-1 peptide-pulsed DC vaccine with or without other peptides, including MUC-1, CEA, or CA-125." (PMID 40723238, 2025). "Moreover, the chemoimmunotherapy regimen consisted of nab-paclitaxel plus gemcitabine combined with WT1-DC vaccination regulated TME and facilitated conversion surgery for advanced pancreatic cancer patients." (PMID 41190066, 2025). "In cancers other than pancreatic cancer, it is presumed that WT1-DC does not increase DTH in cancer patients with strongly suppressed antitumor immunity." (PMID 38143707, 2023). "Interestingly, the analysis identified enrichment of multiple TFs including TCF4, WT1, CEBPD, CEBPB, SUZ12, and ZFP281 across all stages of pancreatic cancer progression." (PMID 30644396, 2019). "Therefore, degrasyn might be a useful therapeutic agent for pancreatic cancer patients with high expressions of USP5 and WT1." (PMID 31845546, 2020). "In pancreatic cancer, expression of BASP1 prolongs survival whereas tumors with no BASP1 but high WT1 expression indicate a poor prognosis." (PMID 31944520, 2020).
desmoplastic small round cell tumor (42 papers, 2004 to 2025). Desmoplastic small round cell tumor (DSRCT) is an aggressive soft tissue cancer that typically arises in serous lined surfaces of the abdominal or pelvic peritoneum, and spreads to the omentum, lymph nodes and hematogenously disseminates especially to the liver. "Desmoplastic small round cell tumours (DSRCTs) represent an ultra-rare subtype of soft tissue sarcoma characterized by a recurrent EWSR1::WT1 oncogenic translocation." (PMID 39921935, 2025). "The 3′ gene partner is important for diagnostic classification as various partners (e.g., FLI1 in Ewing sarcoma, WT1 in desmoplastic small round cell tumor) are characteristic of distinct tumor entities." (PMID 37686670, 2023). "Rearrangements of the RNA binding protein, EWSR1, characterize various malignancies including Ewing sarcoma (EWSR1/ETS), desmoplastic small round cell tumor (EWSR1/WT1), and some acute lymphoblastic leukemias (EWSR1/ZNF384)." (PMID 23637631, 2013). "Desmoplastic Small Round Cell Tumor (DSRCT) is a rare, pediatric cancer caused by the EWSR1::WT1 fusion protein, which alters transcription and drives oncogenesis." (PMID 38575753, 2024). "Desmoplastic Small Round Cell Tumor (DSRCT) is a highly aggressive pediatric cancer caused by a reciprocal translocation between chromosomes 11 and 22, leading to the formation of the EWSR1::WT1 oncoprotein." (PMID 39139449, 2024). "Desmoplastic Small Round Cell Tumor (DSRCT) is a rare, pediatric cancer caused by the EWSR1::WT1 fusion protein." (PMID 38575753, 2024). "He underwent a CT-guided biopsy that revealed a desmoplastic small round cell tumor (DSRCT), showing positivity for EMA, desmin, and nuclear staining for WT1 (carboxy-terminus antibody)." (PMID 27863505, 2016). "Similarly, a nuclear WT1 immunoreactivity is usually obtained by using anti-C-terminus WT1 protein, as a surrogate of the EWS-WT1 fusion transcript, in desmoplastic small round cell tumors (DSRCT)." (PMID 34943491, 2021). "Desmoplastic small round cell tumor (DSRCT) is a rare and aggressive mesenchymal tumor characterized by the expression of the EWSR1::WT1 fusion." (PMID 40852926, 2025).